GPR52 (G protein-coupled receptor 52)
Description:
Gs-coupled receptor activated by antipsychotics reserpine leading to an increase in intracellular cAMP and its internalization. May play a role in locomotor activity through modulation of dopamine, NMDA and ADORA2A-induced locomotor activity. These behavioral changes are accompanied by modulation of the dopamine receptor signaling pathway in striatum. Modulates HTT level via cAMP-dependent but PKA independent mechanisms throught activation of RAB39B that translocates HTT to the endoplasmic reticulum, thus avoiding proteasome degradation.
Tractability: Small molecule: a structure with a bound ligand is known; it belongs to a druggable protein family. Antibody: its Gene Ontology location is reachable by antibodies, with high confidence; UniProt places it where antibodies can reach, with medium confidence; UniProt predicts a signal peptide or a membrane-spanning region. PROTAC: a small molecule that binds it is known.
Target class: Family A G protein-coupled receptor; Membrane receptor
Chemical probes: FTBMT (high quality)
Gene: Protein-coding gene on chromosome 1 (174,447,964 to 174,449,545, forward strand). Ensembl gene ENSG00000203737.
Subcellular location: Cell membrane
Gene Ontology:
Molecular function: G protein-coupled receptor activity; protein binding; G protein-coupled photoreceptor activity
Biological process: response to xenobiotic stimulus; cellular response to light stimulus; G protein-coupled receptor signaling pathway; locomotory behavior; phototransduction; detection of visible light
Cellular component: plasma membrane; membrane
Genetic constraint (gnomAD): Loss-of-function variants: 8 observed, 25.01 expected, observed/expected ratio (o/e) 0.32, 90% interval 0.19 to 0.58. The upper end of that interval is the gene's LOEUF score, 0.58, which puts it in group 2 of 6, group 1 being the genes least tolerant of losing a copy. Missense variants: 412 observed, 470.8 expected, observed/expected ratio (o/e) 0.88, 90% interval 0.81 to 0.95. Synonymous variants: 144 observed, 166.8 expected, observed/expected ratio (o/e) 0.86, 90% interval 0.75 to 0.99.
Homologues: Orthologues: dog GPR52 (97% identical), pig GPR52 (97% identical), mouse Gpr52 (96% identical), rat Gpr52 (95% identical), rabbit GPR52 (90% identical), tropical clawed frog gpr52 (87% identical), zebrafish gpr52 (80% identical), guinea pig GPR52 (69% identical). Paralogues in human: GPR21 (65% identical), CHRM5 (22% identical), CHRM3 (22% identical), HRH2 (22% identical), DRD4 (20% identical), HRH1 (20% identical), HTR4 (20% identical), TAAR6 (20% identical), TAAR9 (20% identical), TAAR8 (20% identical), CHRM1 (19% identical), TAAR1 (19% identical), and 13 more.
Diseases named in the same sentence as GPR52 in open-access papers:
GPR52 is named in the same sentence as 12 diseases in open-access papers, as found by Europe PMC text mining. Sharing a sentence is not in itself a finding about the gene and the disease. The quoted sentences say what the papers report.
Huntington disease (5 papers, 2015 to 2025). Huntington disease (HD) is a rare neurodegenerative disorder of the central nervous system characterized by unwanted choreatic movements, behavioral and psychiatric disturbances and dementia. "GPR52 is predominantly expressed in the brain, particularly in regions associated with symptoms of neuropsychiatric disorders and Huntington’s disease." (PMID 38895631, 2024). "The linked associations of HTT and its regulator GPR52 highlight a clear repurposing opportunity, as GPR52 is already an investigational drug target for Huntington’s disease." (PMID 41001472, 2025). "A global Gpr52 knockout, as well as GPR52 antagonist (E7) treatment has been reported to reduce Huntington’s disease-related symptoms and mutant huntingtin (mHTT) levels in mouse primary striatal neurons." (PMID 36761164, 2022). "Encouragingly, when genetic techniques were used to reduce Gpr52 synthesis in a fruit fly model of Huntington's disease, the treated flies showed fewer movement impairments than flies that had not been treated." (PMID 25738228, 2015). "In addition, reduced levels of Gpr52 were observed to lead to dramatic protective effects in neurons derived from the stem cells of a patient with Huntington's disease." (PMID 25738228, 2015). "Besides psychoses, striatally enriched GPCRs such as GPR52 have been recently reported to modulate Huntington’s disease (HD) phenotypes both in the iPS-derived neurons of a patient and in the Drosophila HD models." (PMID 26101869, 2015). "Furthermore, the identification of GPR52 selective antagonists through high-throughput screening and studies of the structure-activity connection presents novel possibilities for therapeutic approaches for diseases such as Huntington’s disease." (PMID 38895631, 2024). "Furthermore, an involvement of GPR52 in Huntington’s disease has been described." (PMID 36761164, 2022).
schizophrenia (4 papers, 2015 to 2025). A major psychotic disorder characterized by abnormalities in the perception or expression of reality. "From the currently available studies regarding the potential association between GPR expression and schizophrenia, we identified twelve studies out of which two were on GPR-52 expression, four on GPR-85 expression, four on GPR-88 expression, and one on GPR-139 expression." (PMID 38256919, 2024). "An orally available GPR52 agonist (HTL0048149) has recently advanced into Phase I human clinical studies with future potential in schizophrenia, providing direct translational potential for this marker." (PMID 41257792, 2025). "Significant results regarding GPR-52 expression show its distribution in key areas for schizophrenia development: the fact that KO mice show symptoms similar to psychosis but also the fact certain antipsychotics have a direct effect on them." (PMID 38256919, 2024). "Evidence is growing in the field of GPR agonists, with one study suggesting that there are already two distinct GPR-52 agonists that can reverse some of the schizophrenia-like symptoms induced by PCP administration." (PMID 38256919, 2024). "GPR52 represents a promising therapeutic target for the treatment of not only HD but also Parkinson’s disease, schizophrenia, and several other psychiatric disorders." (PMID 34899193, 2021).
Anxiety (2 papers, 2022 to 2025). Intense feelings of nervousness, tension, or panic often arise in response to interpersonal stresses. "There are several orphan GPCRs, such as GPR88, GPR101, GPR52, and GPR6, which display a robust striatal expression and have been associated to anxiety and/or depressive-like states." (PMID 33589739, 2022). "In addition, GPR52 knockout mice displayed reduced anxiety-like symptoms, and a GPR52 inverse agonist was recently found to ameliorate chronic stress-induced deficits in dopaminergic activity and reward motivation." (PMID 41257792, 2025). "GPR52, a Gαs coupled orphan GPCR, is localized uniquely in iMSNs of striatum and GPR52 KO mice demonstrate an anxiety-like phenotype." (PMID 33589739, 2022).
psychosis (2 papers, 2014 to 2024). "In support of our prediction, GPR52 knockout and transgenic mice exhibited psychosis-related and antipsychotic-like behaviors, respectively." (PMID 24587241, 2014).
Autoimmunity (1 paper, 2022). The occurrence of an immune reaction against the organism's own cells or tissues. "While we could not identify an obvious role of GPR52 in in vitro T cell assays and in vivo CNS autoimmunity, it might regulate T cell function in a different context or affect the function of other GPR52-expressing cells." (PMID 36761164, 2022).
experimental autoimmune encephalomyelitis (1 paper, 2022). An autoimmune demyelinating disease of the central nervous system that is produced experimentally in animals by the injection of homogenized brain or spinal cord in Freund's adjuvant. "Moreover, Gpr52 deletion did not modify the clinical disease course of experimental autoimmune encephalomyelitis (EAE)." (PMID 36761164, 2022).
prostate carcinoma (1 paper, 2023). A carcinoma that arises from epithelial cells of the prostate gland. "The study found that GPR52 downregulation involved in aggressive prostate carcinoma recurrence with MTIE; C12orf40 acted as prognostic biomarkers for kidney renal clear cell carcinoma." (PMID 36173462, 2023).
tumor (1 paper, 2017). "In Kaplan-Meier analysis, GPR52 (p = 0.033), in addition to tumor stage (pT; p = 0.020) and grade group (G; p < 0.001), was a significant predictor of BCR." (PMID 28977898, 2017).
GPR52 also shares sentences with these, for which no sentence is quoted: psychiatric disorder (2 papers); cavernous hemangioma (1); Parkinson disease (1); renal fibrosis (1).